NLRP3 (NLR family pyrin domain containing 3)
Diseases named in the same sentence as NLRP3 in open-access papers (continued):
Sharing a sentence is not in itself a finding about the gene and the disease.
rheumatoid arthritis (continued). "We and others have found the combined polymorphism of C10X in CARD8 and Q705K in NLRP3 to be associated with inflammatory diseases and with susceptibility to and severity of rheumatoid arthritis and Crohn's disease." (PMID 25400921, 2014). "In addition to autoinflammatory diseases, NLRP3 inflammasome function has also been implicated in the development of autoimmune diseases like rheumatoid arthritis (RA)." (PMID 27672241, 2016). "Genetic associations (e.g., MEF2D, NLRP3) and comorbidities with autoimmune diseases—including multiple sclerosis (MS), rheumatoid arthritis (RA), systemic lupus erythematosus (SLE), and psoriasis—further support an immunological component in migraine." (PMID 40426647, 2025). "The NLRP3 inflammasome has been associated with the pathogenesis and development of autoimmune diseases, including rheumatoid arthritis (RA), systemic lupus erythematosus (SLE), and ankylosing spondylitis (AS), among others." (PMID 38794217, 2024). "In addition, Pentaxin 3, which is upregulated in the plasma of patients with rheumatoid arthritis, can act synergistically with the ligand C1q to activate NLRP3 inflammasome, causing caspase-1-mediated pyroptosis and inflammatory cytokines, the degree of which was consistent with disease activity." (PMID 37386410, 2023). "Interestingly, A20 deficiency in macrophages significantly enhanced NLRP3 inflammasome-mediated caspase-1 activation, pyroptosis, and IL-1β secretion, and negative regulation of the NLRP3 inflammasome by A20 protected against rheumatoid arthritis." (PMID 35794098, 2022). "However, subgroup analysis by disease type showed that NLRP3 rs35829419 A allele may have a significant protective effect on rheumatoid arthritis (RA) susceptibility [A vs. C: 0.74 (0.57-0.96)]." (PMID 34367252, 2021). "However, excessive activation of the NLRP3 inflammasome results in development of several inflammatory diseases, including septic shock, type 2 diabetes, cryopyrin-associated periodic syndromes, rheumatoid arthritis, and Alzheimer’s disease." (PMID 30823406, 2019). "The abnormal activation of the NLRP3 inflammasome has been confirmed in inflammatory diseases such as rheumatoid arthritis." (PMID 41463300, 2025). "In this study, we investigated the inhibitory effects of emodin on pyroptosis in rheumatoid arthritis (RA) synovial cells by modulating the HIF-1α/NLRP3 inflammasome pathway and mitochondrial autophagy." (PMID 40728955, 2025). "In rheumatoid arthritis, treatment with an NLRP3 inhibitor improved inflammation indicating a crucial role of IL-1β in disease pathogenesis." (PMID 40791588, 2025). "Researchers have observed in a mouse model of rheumatoid arthritis (RA) thatIL-6 can activate the NLRP3 inflammasome in the presence of ATP." (PMID 41209134, 2025). "NLRP3 inflammasome activity has been found to be greater in cardiomyocytes of patients with rheumatoid arthritis and a history AF compared to sinus rhythm controls." (PMID 39139903, 2024). "Previous studies have shown that miR-223-3p can specifically target the 3’UTR of NLRP3 and inhibit inflammatory reactions in inflammatory diseases such as rheumatoid arthritis, acute and chronic liver injury, tuberculosis." (PMID 38448875, 2024). "As reported, miR-223-3p inhibits fibroblast-like synoviocyte pyroptosis and proliferation and inflammatory responses of fibroblast-like synoviocyte in rheumatoid arthritis by targeting NLRP3." (PMID 38616256, 2024). "Genetic experiments showed that NLRP3 inflammasome activation was required for the development of rheumatoid arthritis and cartilage destruction in the mice." (PMID 36669831, 2023). "For example, the combined application of mangiferin and cinnamic acid has exhibited the capacity to impede TLR4/NLRP3-activated pyroptosis, consequently alleviating rheumatoid arthritis." (PMID 37766966, 2023).
rheumatoid arthritis (continued). "Necroptosis machinery was shown to lead to NLR family pyrin domain containing 3 (NLRP3) inflammasome activation within macrophages/bone marrow-derived monocytes in the context of autoimmune diseases (e.g., rheumatoid arthritis, dermatitis)." (PMID 37935670, 2023). "Aberrant functions of intracellular NLRP3 inflammasomes promote the occurrence and development of autoimmune diseases, with the majority of studies currently focused on rheumatoid arthritis, systemic lupus erythematosus and systemic sclerosis." (PMID 37960237, 2023). "In rheumatoid arthritis, the deletion of NLRP3 and its downstream components significantly reduces inflammation and cartilage destruction." (PMID 37370025, 2023). "It has been reported in the literature that Sargentodoxa cuneata can modulate the NF-κB/NLRP3 signaling pathway for the treatment of rheumatoid arthritis." (PMID 38005385, 2023). "HCQ is an anti-malarial agent, which is also commonly used to treat multiple autoinflammatory diseases, including those to which the NLRP3 inflammasome is known to contribute: rheumatoid arthritis, systemic lupus erythematosus, and Sjögren’s syndrome." (PMID 36523654, 2022). "Accordingly, the NLRP3 inflammasome plays a vital role in immune regulation through leading to autoimmune diseases by its dysfunction or hyperactivation, and rheumatoid arthritis is one of them." (PMID 35833125, 2022). "Future studies will elucidate the exact role of the NLRP3 inflammasome in regulating bone remodeling in infectious, as well as inflammatory, bone diseases such as rheumatoid arthritis and osteoporosis." (PMID 35682777, 2022). "Abnormal activation of NLRP3 is considered as a key in several autoimmune diseases such as rheumatoid arthritis (RA), systemic lupus erythematosus (SLE), as well as SSc." (PMID 35974386, 2022). "The function of NLRP3 inflammasome and its significant role have been demonstrated in several autoimmune diseases, including rheumatoid arthritis, ankylosing spondylitis, and multiple sclerosis." (PMID 35965334, 2022). "It is known that tofacitinib also restores the balance of Treg/Th17 cells in rheumatoid arthritis and alleviates the inflammatory response by inhibiting NLRP3 inflammasome." (PMID 35833125, 2022). "MCC950 ameliorates rheumatoid arthritis injury by inhibiting NLRP3 activation and subsequent IL-1β production." (PMID 35833125, 2022). "NLRP3 inflammasome-driven inflammation accompanies the pathogenesis of autoimmune diseases which includes rheumatoid arthritis and makes NLRP3 inflammasome an attractive drug target." (PMID 35833125, 2022). "The expression of NLRP3 inflammasome was upregulated in patients with rheumatoid arthritis (RA) and ankylosing spondylitis (AS), and this was associated with high levels of pro-inflammatory cytokines." (PMID 33215255, 2021). "Conversely, transcription of the genes of the components of the NLRP3 inflammasome was substantially increased in patients with rheumatoid arthritis." (PMID 33534121, 2021). "The active ingredients of LF were investigated using network pharmacology and molecular docking methods, and their inhibition of NLRP3 inflammasome activation was verified in the human rheumatoid arthritis fibroblast-like synovial cells (RA-FLS) model." (PMID 34583676, 2021). "It has been reported that NLRP3 knockdown by using siRNA in CD4 T cells isolated from rheumatoid arthritis (RA) patients suppressed Th17 differentiation." (PMID 34234669, 2021). "Several studies demonstrated the association of NLRP3 rs35829419 C>A polymorphism with the increased risk of colorectal cancer, HIV-1 infection, rheumatoid arthritis, leprosy, and atopic dermatitis." (PMID 30728751, 2019). "We demonstrated that methotrexate play an inhibitory effect on rheumatoid arthritis swelling and inflammation by downregulating NF-κB and NLRP3/Caspase-1 pathways and potentially affecting the activity of caspase-1." (PMID 30249062, 2018).
rheumatoid arthritis (continued). "Recently, A20/TNFAIP3 was found to be a negative regulator of the NLRP3 inflammasome, and specific deletion of A20 in myeloid cells resulted in spontaneous arthritis in mice that resembled human rheumatoid arthritis." (PMID 30072988, 2018). "It remains, however, largely unknown how NETs trigger NLRP3 inflammasome activation in rheumatoid arthritis." (PMID 40791588, 2025). "Additionally, CA inhibits NLRP3-derived IL-1β production, a critical driver of inflammation in rheumatoid arthritis." (PMID 39684628, 2024). "In addition to anti-IL-1 agents, inhibitors of NLRP3 and caspase-1, two central proteins of the NLRP3 inflammasome, were suggested as new possible treatments for gouty and rheumatoid arthritis." (PMID 36675455, 2023). "A20 is a novel negative regulator of NLRP3 inflammasome activation, and targeting A20 expression may provide a new strategy for the treatment of inflammatory bone diseases such as rheumatoid arthritis." (PMID 37954594, 2023). "For example, the NLRP3 inflammasome plays a role in the pathogenesis of rheumatoid arthritis." (PMID 35429346, 2022). "Icariin regulates the miR-223-3p/NLRP3 signaling axis to relieve rheumatoid arthritis." (PMID 36212957, 2022). "Here we discuss the current progress of the NLRP3 inflammasome in rheumatoid arthritis." (PMID 35833125, 2022). "Dysregulation of NLRP3 inflammasome has also been suggested in the pathogenesis of rheumatoid arthritis (RA), a chronic autoimmune disease characterized by persistent synovial inflammation in small diarthrodial joints, progressive cartilage, bone destruction, and autoantibody production." (PMID 35754962, 2022). "Current clinical trials of NLRP3-targeting kinase inhibitors primarily focus on tumors (such as mantle cell lymphoma) and autoimmune diseases (such as rheumatoid arthritis), and whether NLRP3 phosphorylation is a practical treatment target needs further study." (PMID 36688154, 2022). "The growing appreciation of the NLRP3 inflammasome activation and bioactive IL‐1β release in acute gouty inflammation or in the more chronic rheumatoid arthritis has prompted studies of agents blocking the IL‐1β receptor or soluble IL‐1β (canakinumab, rilonacept, and anakinra)." (PMID 35438238, 2022). "Canakinumab has been considered the preferred treatment option due to its longer half-life of 26 days (as compared to anakinra) and has been shown to reduce the incidence of other inflammatory NLRP3-­related diseases, including pustular psoriasis and rheumatoid arthritis." (PMID 35663672, 2022). "Both CY-09 and tranilast (TR) bind directly to the ATP-binding motif of the NACHT domain of NLRP3 to inhibit ATPase activity and thus prevent the assembly of NLRP3 inflammasome, which may be promising in the management of rheumatoid arthritis." (PMID 35833125, 2022). "ACPA promotes IL-1 production in rheumatoid arthritis by activating the NLRP3 inflammasome." (PMID 35833125, 2022). "NLRP3 inflammasome plays an important role in the pathogenesis of rheumatoid arthritis (RA)." (PMID 34750358, 2021). "Pydc3 is a component of the NLRP3 inflammasome that has been shown to play a T cell-intrinsic role in Th17 differentiation in experimental autoimmune encephalitis (EAE) as well as in the regulation of Th17 differentiation in patients with rheumatoid arthritis." (PMID 33730591, 2021). "Anakinra, an IL-1 receptor antagonist used for rheumatoid arthritis treatment and glyburide, a sulfonylurea medication inhibiting NLRP3 inflammasome activation by preventing the secretion of IL-1β, are just two drugs sustaining the use of NLRP3 inflammasome-targeted therapies for T2D and CMS." (PMID 33172097, 2020). "Moreover, ICA upregulates the miR-223-3p/NLRP3 pathway to induce apoptosis in rheumatoid arthritis fibroblast-like synoviocytes (RA-FLS), suggesting that miR-223-3p may be a potential target of ICA in RA therapy." (PMID 40872565, 2025).
rheumatoid arthritis (continued). "In rheumatoid arthritis (RA), the biomarker pentraxin 3, along with its ligand C1q, has been reported to activate NLRP3." (PMID 38172822, 2024). "The NLRP3 inflammasome, plays a critical role in the pathogenesis of rheumatoid arthritis (RA) by activating inflammatory cytokines such as IL1β and IL18." (PMID 39791728, 2024). "The potential inhibitors of the components of the NLRP3 inflammasome in rheumatoid arthritis (RA) and its comorbidities." (PMID 38203796, 2024). "Furthermore, NLRP3 inflammasome activation has been reported, which could modulate Th17 cell differentiation in patients with rheumatoid arthritis." (PMID 37686332, 2023). "Additionally, the formation of fetuin-A-based calcium and phosphate-containing matter that functions to prevent extraosseous calcification in vivo increases extracellular Ca2+, thus, inducing CaSRs signaling and leading to NLRP3 inflammasome activation in rheumatoid arthritis." (PMID 35883561, 2022). "In addition, higher levels of NLRP3 and caspase-1 were observed in patients with rheumatoid arthritis than in patients with degenerative arthritis, and it was found that the administration of selective NLRP3 inhibitors reduced redness and cartilage degradation." (PMID 36619197, 2022). "Interestingly, it was observed that NLRP3 and CARD8 polymorphisms are significantly connected with susceptibility to some inflammatory diseases, including psoriatic juvenile idiopathic arthritis and rheumatoid arthritis." (PMID 34072753, 2021). "It is also believed that NLRP3 inflammasomes are closely related to the onset of many diseases, including kidney diseases, cardiovascular diseases, rheumatoid arthritis (RA), asthma, gout, HIV infection, and Alzheimer's disease." (PMID 31427885, 2019). "NLRP3 also regulates the differentiation of Th17 cells in rheumatoid arthritis (RA)." (PMID 39621557, 2025). "We have previously demonstrated that TAK1 inhibition by LL-Z1640-2 (LLZ) reduced joint inflammation and bone destruction by inhibiting NLRP3 inflammasome and TNF-α expression in collagen-induced arthritis, a mouse model of rheumatoid arthritis." (PMID 38891908, 2024). "This study found that HCQ significantly inhibited the expression of pyroptosis markers GSDMD and NLRP3 in microglia, a mechanism similar to HCQ's inhibition of cell death pathways in rheumatoid arthritis." (PMID 39694827, 2024). "We have previously demonstrated that TAK1 inhibition by LLZ reduced joint inflammation and bone destruction by inhibiting NLRP3 inflammasome and TNF-α expression in collagen-induced arthritis, a mouse model of rheumatoid arthritis." (PMID 38891908, 2024). "Studies have found that the NLRP3 inflammasome is highly activated in the synovium of patients with RA and collagen-induced rheumatoid arthritis model mice and that NLRP3 activation plays an important role in the pathogenesis of RA." (PMID 36378463, 2023). "Autoimmune disorders, of which rheumatoid arthritis (RA), systemic lupus erythematosus (SLE), inflammatory bowel disease (IBDs), and so on are the most commonly seen, show strong connection with NLRP3 inflammasome." (PMID 37817895, 2023). "NLRP3 (NOD-, LRR-, and pyrin domain-containing protein 3), which contributes to the occurrence of many inflammatory diseases such as rheumatoid arthritis (RA), atherosclerosis, and gout, has received extensive attention in recent years." (PMID 34777685, 2021). "Importantly, dysfunctional NLRP3 inflammasomes are drivers of autoimmune diseases such as gout, rheumatoid arthritis (RA) and lupus." (PMID 31013297, 2019). "While a huge part of current and past research focused on NLRP3 inflammasomes, it could be shown that the G allele of a polymorphism (rs878329) in the NLRP1 promoter in the Chinese population up-regulates gene transcription and puts patients at risk for developing rheumatoid arthritis." (PMID 31795299, 2019).
rheumatoid arthritis (continued). "Moreover, our results establish human soluble FADD as a marker of joint inflammation during rheumatoid arthritis (RA) and gout attack, two inflammatory rheumatic diseases involving the NLRP3 inflammasome." (PMID 30804327, 2019). "TRIM3 overexpression has an inhibitory effect on the proliferation and cytokine secretion of fibroblast-like synoviocytes in rheumatoid arthritis and can protect against LPS-induced acute kidney injury by inhibiting the IRF3 pathway and NLRP3 inflammasome activation." (PMID 37520369, 2023). "Among these molecules, gallic and butyric acids, for example, demonstrated their potential in modulating NLRP3 markers in intestinal inflammation, while the JAK (Janus kinase) inhibitor tofacitinib ameliorates symptoms in rheumatoid arthritis by inhibiting NLRP3 inflammasome." (PMID 34681901, 2021). "In disorders such as rheumatoid arthritis (RA), osteoarthritis (OA), phlebitis, and IBD, GBP5 activates the NLRP3 inflammasome, thereby increasing IL-1β and IL-18 production, which exacerbates local inflammation (55, 138, –, 140)." (PMID 40788157, 2025). "Currently, the role of NLRP3 inflammasome and COX-2 has been documented in autoimmune diseases such as rheumatoid arthritis (RA) and systemic lupus erythematosus (SLE)." (PMID 34790822, 2021). "Koumine (KM), one of the primary constituents of Gelsemium elegans, has been used for the treatment of inflammatory diseases such as rheumatoid arthritis, but whether KM impacts the activation of the NOD-like receptor protein 3 (NLRP3) inflammasome remains unknown." (PMID 33542692, 2020). "In the synovium of rheumatoid arthritis (RA) rats, hypoxic TGF-β1 induction increased succinate accumulation due to the reversal of succinate dehydrogenase (SDH) activation and induced NLRP3 inflammasome activation in a manner dependent on HIF-1α induction." (PMID 28003810, 2016).